HLA-G (major histocompatibility complex, class I, G)
Diseases named in the same sentence as HLA-G in open-access papers (continued):
Sharing a sentence is not in itself a finding about the gene and the disease.
melanoma (continued). "Moreover, it could be shown that inflammatory TILs itself may express HLA-G, as has been demonstrated, e.g., in melanoma." (PMID 31013867, 2019). "Furthermore, soluble HLA-G serum levels have been reported to be elevated in melanoma patients." (PMID 27999823, 2016). "Therefore, it can be speculated that high expression of HLA-G, as well as regulatory T cells, might contribute to a poor prognosis in patients with malignant melanoma." (PMID 27999823, 2016). "We cloned the ten most frequent HLA-G 5′URR haplotypes to evaluate their activity on a luciferase reporter gene in HLA-G+ cell lines (JEG-3/choriocarcinoma and FON+/melanoma)." (PMID 29618829, 2018). "Examples include PD-L1, HLA-G and CD86, shown to induce immunosuppression in NK and CD8+ cells following their cross-dressing with membranes taken from melanoma or multiple myeloma." (PMID 25671577, 2015). "Although not significant, LEVs-HLA-G+ was slightly increased in nevi group with counts of 2.44E + 04 (1.36E + 04-4.68E+04)/mL, while melanoma showed 1.44E + 04 (9.06E + 03-3.27E+04) count/mL (p=0.09)." (PMID 41268555, 2025). "In the same way, LEVs-HLA-G+ and int-HLA-G were increased when nevi participants experienced a cancer diagnosis, but not in melanoma participants." (PMID 41268555, 2025). "Complementary studies in control and HLA-G-depleted parental lung and melanoma BMICs showed that HLA-G ablation resulted in reduced p-STAT3 levels in lung and melanoma BMICs when compared to their control counterparts, demonstrating a bona fide role for HLA-G in STAT3 signaling activation in BMICs." (PMID 36780531, 2023). "Co-culture of NK cell lines with HLA-G-expressing melanoma M8 cells restored the expression of KIR2DL4 or ILT2 on NK cells, and NK cells could use the trogocytosis to acquire HLA-G from tumor cells." (PMID 33193435, 2020). "The immune modulatory functions of HLA-E were determined in the stable transfected HLA-E overexpressing (HLA-G negative) melanoma cell line BUF1088." (PMID 27589686, 2016). "Controversies exist regarding the detection of HLA-G protein expression in melanoma tumor biopsies, while nearly all melanoma cell lines seem to be negative." (PMID 27999823, 2016). "Regarding cancer, in 1998, it was first found that HLA-G expression is restricted to melanoma lesions, but not in adjacent normal skin tissues, and that HLA-G could inhibit NK cell function to enhance cancer immune evasion." (PMID 41181133, 2025). "To elucidate whether HLA-G stimulates STAT3 signaling in BMICs via SPAG9, we generated pooled SPAG9 knockout in HLA-G OE lung BMICs and probed for the expression of p-STAT3 (Y705) in control and SPAG9 knockout lung and melanoma BMICs." (PMID 36780531, 2023). "We also reveal the transcriptional profiles of premetastatic and non-premetastatic lung, breast, and melanoma BMICs and demonstrate putative brain metastatic functions for HLA-G—one of the genes found to be commonly up-regulated in the premetastatic BMIC cohorts." (PMID 36780531, 2023). "Similar findings, such as the fact that HLA-G and paired immunoglobulin-like receptor B (PIR-B, murine homolog of human ILT receptors) engagement expanded the population of CD11b+Gr1+PIR-B+ MDSCs in an M8-HLA-G1 (human melanoma cell line) tumor-bearing mouse model, have also been reported." (PMID 30319626, 2018). "Nonetheless, whether or not this site is involved in the DFX-induced HLA-G transcription in melanoma cells, is still unsolved." (PMID 27577073, 2016). "Although HLA-G expression has been documented in several other cancer sites, i.e. cervical cancer, melanoma, breast, colorectal, gastric, esophageal, lung, and other cancers, the implications of HLA-G methylation on the expression of the protein have not been described." (PMID 23265140, 2012). "Furthermore, invasiveness of lesions (i.e., whether melanoma was in situ or invasive) did not influence any of the HLA-G forms (LEVs-HLA-G+, sHLA-G, int-HLA-G, p>0.05)." (PMID 41268555, 2025).
melanoma (continued). "Although IL-6 serum levels were not statistically different between nevi and melanoma patients in our cohort, this preliminary in vitro assay suggests that besides the known HLA-G role, in melanoma, it may influence immune cells in the tumor microenvironment to produce this cytokine." (PMID 41268555, 2025). "It has been shown that PBNK cells may lose their cytotoxic ability by acquiring HLA-G, a non-classical MHC class I molecule, from transfected melanoma cell lines through trogocytosis, while the cytotoxic ability can be reversed once the phagocytosed HLA-G is degraded or turned over." (PMID 35720413, 2022). "We used four different cell lines that express HLA-G (choriocarcinoma JEG-3 and melanoma FON) or not (Melanoma M8 and glioma U251MG) to focus on HLA-G 3’UTR haplotypes that are frequently found worldwide, namely UTR-1, UTR-2, UTR-3, UTR-4, UTR-5, UTR- 18 and UTR-7." (PMID 28045999, 2017).
preeclampsia (47 papers, 2011 to 2025). Preeclampsia is a hypertensive disorder of pregnancy that is characterized by new-onset hypertension with proteinuria presenting after 20 weeks of gestation, and depending on mild or severe forms may initially present with severe headache, visual disturbances, and hyperreflexia. "The presence of HLA-G has been associated with a lower risk of immune-mediated pregnancy disorders, such as recurrent miscarriage and preeclampsia." (PMID 39767812, 2024). "Potential biomarkers such as MMPs, soluble HLA-G, and human chorionic gonadotropin (hCG) hold promise for predicting preeclampsia and its associated complications." (PMID 38674114, 2024). "Abnormal expression and genetic polymorphisms of HLA-G have been found to correlate closely with preeclampsia and recurrent miscarriage." (PMID 36700203, 2022). "Some meta-analyses have confirmed the association between HLA-G polymorphisms with susceptibility to preeclampsia and recurrent miscarriage (RM)." (PMID 36532068, 2022). "Fetal HLA-G variants from fathers increase immune incompatibility with mothers and are also significantly associated with preeclampsia in multiple pregnancies." (PMID 35360083, 2022). "HLA-G polymorphisms are associated with abnormal HLA-G levels and linked to reproductive disorders such as implantation failure, recurrent miscarriage, preeclampsia, and placental abruption." (PMID 36532068, 2022). "combined implantation failure, preeclampsia, recurrent miscarriage, and spontaneous miscarriage as reproductive disorders and performed a meta-analysis; they found that the HLA-G 14bp ins variant is associated with reproductive disorders." (PMID 36532068, 2022). "Clinically, downregulation of HLA-G is reported to be associated with poor placentation in preeclampsia and immune cell infiltration during ascending infection." (PMID 34685432, 2021). "Several studies also investigated the expression of membrane-bound and soluble HLA-G in umbilical cord blood and its association with preeclampsia; however, its expression was significantly lower than in maternal blood." (PMID 34685432, 2021). "Our study suggests that long-read sequencing of HLA-G will provide clues for characterizing HLA-G variants that are involved in the pathophysiology of preeclampsia." (PMID 33208885, 2020). "In this study, we determined the contribution of specific HLA-G polymorphisms on the risk of developing preeclampsia in HIV-infected and uninfected South Africans of African ancestry." (PMID 32596279, 2020). "The abnormal expression and polymorphisms of HLA-G are related to adverse pregnancy outcomes such as preeclampsia (PE) and recurrent spontaneous abortion (RSA)." (PMID 33193435, 2020). "The literature provides evidence that the polymorphic variants of the HLA-G antigen involve complications in pregnancy, such as recurrent spontaneous abortion and preeclampsia." (PMID 30893814, 2019). "Researchers have reported a significant association between the single nucleotide polymorphism (SNP) at position 1754 in exon 8 in the 3′-UTR (untranslational region) of the HLA-G gene and the risk of preeclampsia." (PMID 30893814, 2019). "DNA methylation is an important mechanism for regulating gene expression and a few reports suggest that methylation of the HLA-G promoter is associated with lower secretion of HLA-G in women with preeclampsia." (PMID 30158921, 2018). "Fetal HLA-G variants from the father increased the immune incompatibility with the mother and are also significantly associated with preeclampsia in multigravida pregnancies." (PMID 30666213, 2018). "The presence of fetal variants of HLA-G from the father and those outside the mother generate a paternal-fetal susceptibility component for the development of preeclampsia." (PMID 30666213, 2018).
preeclampsia (continued). "Reduction in HLA-G, both maternally through functional single nucleotide polymorphisms in the HLA-G gene or reduction in fetally derived trophoblasts, has been related to an increased incidence of preeclampsia." (PMID 28130428, 2017). "The HLA-G 14 bp ins/ins genotype has been associated to increased susceptibility to spontaneous abortion, unsuccessful in vitro fertilization, preeclampsia, recurrent miscarriage, and autoimmune diseases." (PMID 28655969, 2017). "Quach and colleagues have addressed the correlation between SNP in the 3′UTR of the HLA-G gene and an increased risk of preeclampsia." (PMID 27652273, 2016). "Accordingly, lowered HLA-G expression was associated with the occurrence of preeclampsia and intrauterine growth retardation." (PMID 25243172, 2014). "First, a direct association between reduced HLA-G expression in term placentas and preeclampsia has been demonstrated with in situ hybridization, immunohistochemistry on frozen sections, and with a ribonuclease protection assay." (PMID 25566263, 2014). "Some studies support the finding that decreased HLA-G production plays a role in the pathophysiology of preeclampsia by causing a decrease in maternal immune tolerance to invasive trophoblasts resulting in defective trophoblastic invasion." (PMID 24098421, 2013). "Among the fetal HLA-G gene polymorphisms, rs9380142 (A vs. G: OR = 2.802, 95% CI = 1.761–4.458) and rs1063320 (G vs. C: OR = 1.807, 95% CI = 1.144–2.852) differed between the preeclampsia group and the control group." (PMID 39144721, 2024). "Therefore, we suggest that fetal HLA-G gene polymorphisms are associated with the development of preeclampsia and are risk factors for disease development." (PMID 39144721, 2024). "Thus, polymorphisms causing low levels of HLA-G expression are more likely to result in spontaneous abortions, preeclampsia, and transplant rejection." (PMID 39355248, 2024). "Furthermore, alterations of HLA-G expression during pregnancy are associated with adverse pregnancy outcome such as preeclampsia." (PMID 35111157, 2021). "In this study, we investigated whether there was a genetic association of the six HLA-G gene polymorphisms with the risk of preeclampsia development in HIV-infected and uninfected South African women of African ancestry." (PMID 32596279, 2020). "This study has shown that HIV infection may be associated with selected HLA-G gene polymorphisms and the risk of preeclampsia in HIV-infected South Africans of African ancestry." (PMID 32596279, 2020). "Finally, a positive correlation between polymorphisms of HLA-G gene and infertility, preeclampsia, and abortion has been further confirmed." (PMID 27652273, 2016). "An association between HLA-G and preeclampsia is supported by several findings." (PMID 25566263, 2014). "In addition, HLA-G genetic variants are associated with both membrane-bound and soluble forms of HLA-G, and, in some studies, with preeclampsia." (PMID 25566263, 2014). "The 1597ΔC null mutation is rare in Europeans but more common in other global populations, which emphasizes that ethnic difference or demographic factors should be considered in future study set-up, or when interpreting meta-studies on the association of HLA-G polymorphisms with preeclampsia." (PMID 25566263, 2014). "Indeed, the presence of an Adenine at position +3187 is associated with decreased mRNA stability in vitro and low HLA-G production by the placenta during pregnancy, favoring the development of preeclampsia." (PMID 24498610, 2013). "Low HLA-G expression levels at the fetal-maternal interface were associated with pregnancy complications, such as preeclampsia and interestingly, higher levels of miR-152 were detected in preeclamptic placentas and high levels of miR-148a were detected in preterm labor placenta." (PMID 22438923, 2012).
preeclampsia (continued). "HLA-G is important for a successful pregnancy and low expression levels of HLA-G at the fetal-maternal interface are associated with pregnancy complications, such as preeclampsia." (PMID 22438923, 2012). "Among the four SNP loci in the paternal HLA-G gene, the frequencies of the rs1630185G (OR = 1.644, 95% CI = 1.005∼2.688, p = 0.046) and rs1130363A (OR = 1.644, 95% CI = 1.005∼2.688, p = 0.046) alleles were lower in the preeclampsia group than in the control group." (PMID 39144721, 2024). "Interestingly, a small pilot study has linked the presence of HCMV sequences and certain HLA-G alleles with increased risk of preeclampsia, and there might be some evidence for an association between CMV infection and preeclampsia." (PMID 24741608, 2014). "The yellow clustering group focused on trophoblast, preeclampsia, and human leukocyte antigen G (HLA-G)." (PMID 40034381, 2025). "Soluble HLA-G, crucial for maternal–fetal immune tolerance, is reduced in preeclampsia, contributing to impaired immune responses and defective arterial remodeling." (PMID 38674114, 2024). "In conclusion, our findings underscore significant HLA-G gene polymorphisms in fetuses within the Chinese Han population, implicating fetal HLA-G as pivotal in preeclampsia pathogenesis." (PMID 39144721, 2024). "Despite the lack of a direct association between maternal KIR gene polymorphisms and preeclampsia, specific maternal KIR2DL4 and fetal HLA-G combinations warrant further exploration." (PMID 39144721, 2024). "The genotype frequencies of rs1630185 and rs1130363 in the paternal HLA-G gene were both significantly different between the preeclampsia group and the control group (p = 0.01 and p = 0.01)." (PMID 39144721, 2024). "These manuscripts primarily focused on HLA-G expression (33 studies) and its role in preeclampsia (30 studies), but also looked at its role in immune cell activation, regulation of inflammation, and trophoblast invasion." (PMID 34685432, 2021). "Circulating soluble HLA-G (sHLA-G) is also lower in preeclampsia throughout all trimesters, compared to pregnancies that remain normotensive." (PMID 34970270, 2021). "HLA-G is expressed in pregnancies by cells of the trophoblast at the maternal–fetal interface; in preeclampsia and recurrent spontaneous abortion the expression levels of HLA-G are decreased." (PMID 32575403, 2020). "HLA-G, part of the major histocompatibility complex (MHC), is associated with the risk of developing preeclampsia (PE)." (PMID 32596279, 2020). "Decreased expression of HLA-G has been observed under conditions posing a threat to pregnancy, such as preeclampsia and recurrent spontaneous abortion, which confirms its protective effect on pregnancy." (PMID 30893814, 2019). "In another study, decreased HLA-G levels in the urine of women correlated with pregnancy disorders, such as recurrent spontaneous abortion and preeclampsia." (PMID 31052398, 2019). "There are several studies suggesting low or reduced levels of sHLA-G in preeclampsia patients and reduced levels of HLA-G mRNA has been observed in placentas of preeclamptic women." (PMID 30483272, 2018). "Reduced levels of expressed HLA-G and its soluble concentration in maternal plasma were observed in cases of miscarriage and preeclampsia, suggesting that inadequate immune recognition and tolerance contributed to pregnancy complications in these women." (PMID 30079067, 2018). "Recently, associations between preeclampsia and SNPs in the 3′ untranslated region (3′UTR) of HLA-G have been observed." (PMID 29540242, 2018). "In this study, we compared nine SNPs in the 3′UTR region of HLA-G between spontaneous preterm birth and preeclampsia in gestational age matched placentas." (PMID 29540242, 2018). "In line with this conclusion, in women with preeclampsia a subset of decidual CD14+DC-SIGN+ APCs with reduced HLA-G and ILT4 expression and impaired ability to promote Tregs in vitro have been identified." (PMID 29686676, 2018).